SIRT1 (sirtuin 1)
Diseases named in the same sentence as SIRT1 in open-access papers (continued):
Sharing a sentence is not in itself a finding about the gene and the disease.
tumor (continued). "In addition, we investigated the relation between the combined expression levels of LSD1, HDAC2 and SIRT1 and tumor cell proliferation, assessed by ki-67 expression, which is another marker of aggressive tumors." (PMID 25139823, 2014). "The functional role of SIRT1 in cancer is controversial, for it may act as a tumor promoter or suppressor depending on tumor type." (PMID 24416313, 2014). "No other significant associations were observed between SIRT1 expression and age, gender, differentiation, weight loss, tumor location, or length of tumor (P > 0.05)." (PMID 25922660, 2014). "In addition, SIRT1 is overexpressed in chemoresistant cells, and inhibiting SIRT1 can suppress tumor growth in some models." (PMID 25119136, 2014). "Our results indicate that SIRT1 protein may have a tumor-promoting function in ESCC patients, as its positive expression was significantly correlated with T status and stage." (PMID 25922660, 2014). "SIRT1 operates as both a tumor suppressor and oncogenic factor depending on the cell context." (PMID 24742694, 2014). "SIRT1 has been shown to act as both tumor promoter and tumor suppressor." (PMID 24603648, 2014). "However, the role of SIRT1 is quite puzzling as there is an ongoing debate regarding its role as a tumor suppressor versus tumor promoter." (PMID 24743044, 2014). "This suggests that Sirt1 may have the properties of a tumor suppressor gene and several studies have suggested that this may be the case." (PMID 25380034, 2014). "The abundance or activity of SIRT1 has been reported to decrease or increase in tissues following treatment with HFD or resveratrol respectively, so we set out to determine if the tumor promoting or inhibiting effects of these treatments on oncogenesis is dependent on SIRT1." (PMID 25380034, 2014). "Therefore a thorough understanding of how SIRT1 regulates tumor progression will provide crucial information for bringing sirtuin inhibitors into the clinical use in the future." (PMID 24416313, 2014). "SIRT1 also may have suppressive activity in tumor cell growth by suppressing NF-κB, a transcription factor that plays a central role in the regulation of innate and adaptive immune responses and carcinogenesis." (PMID 25486244, 2014). "SIRT1 expression was significantly overexpressed in the tumor tissues and HCC cell lines." (PMID 25522783, 2014). "Particularly, in TNM classification, Sirt1-positive expression is more closely associated with lymph node invasion and metastasis, but not with tumor size." (PMID 24959282, 2014). "Additionally, our results showed a significantly high LVD and positive LVI in patients with SIRT1 positive expression, indicating an important role for SIRT1 in promoting tumor lymphangiogenesis and lymphatic metastasis." (PMID 25922660, 2014). "In addition, the SIRT1 activator SRT1720 promotes tumor cell migration and lung metastases in a murine breast cancer model." (PMID 24280167, 2013). "However, when there are oncogenic signals, SIRT1 served to promote the proliferation or survival of tumor cells." (PMID 24019980, 2013). "The regulation of SIRT1 also supports a role in tumour growth and survival." (PMID 24258275, 2013). "Additionally, tumors in SIRT1-deficient mice exhibited markedly increased numbers of cells undergoing apoptosis, suggesting that SIRT1 contributes to tumor growth by enabling survival of tumor cells." (PMID 23799088, 2013). "However, in the Sirt1-depleted xenografts, the inhibitory effects of Res on tumor growth were rescued (Res+Si vs Res+Ci: 1.2313±0.1777 cm3 vs 0.68±0.0672 cm3, P<0.001, Res+Si vs control: 1.2313±0.1777 cm3 vs 1.4288±0.1741 cm3, P = 0.123)." (PMID 24278101, 2013). "In addition, SIRT1 inhibitor nicotinamide delayed tumor initiation in c-Myc mediated liver-specific tumorigenesis in a murine model." (PMID 24019980, 2013).
tumor (continued). "However, in a colon cancer mouse model, increased SIRT1 expression suppresses cell proliferation and tumor formation." (PMID 23460888, 2013). "However, it is known that the oncogenic role of sirtuin 1 is tumor- and context-specific, and the opposite relation between the histone deacetylase and c-Myc has already been described, indicating that sirtuin 1 promotes c-Myc instability." (PMID 24127549, 2013). "Abrogation of Sirt1 led to growth inhibition and reduced engraftment of the tumor cells." (PMID 24088390, 2013). "FOXO-deacetylation by SIRT1 may therefore also contribute to longevity and survival of tumor cells, questioning the general view of FOXOs as tumor suppressor proteins (reviewed in." (PMID 23801966, 2013). "In addition, SIRT1 induces expression of tumor progressing targets such as constitutive Wnt signaling pathway and survivin." (PMID 24019980, 2013). "There is evidence that Sirt1 is required for CR-induced lifespan extension in mice suggesting that Sirt1 may be a tumor suppressor gene." (PMID 24278473, 2013). "However, there are additional conflicting reports regarding the tumor suppressing capability of SIRT1." (PMID 23024800, 2012). "Given the multitude of downstream factors targeted by SIRT1 for deacetylation, SIRT1 has been hypothesized to act as a key regulator of several pathways involved in tumor growth and vascularization." (PMID 23028940, 2012). "Since it has been previously reported that the biologic effects of SIRT1 may vary according to species and tumor types, we next sought to determine the effect of SIRT1 manipulation in two well characterized human HCC cell lines." (PMID 23024800, 2012). "Our findings suggest that pharmacological- or molecular-based blockade of SIRT1 activity may represent a promising and novel approach for blocking tumor progression." (PMID 23028940, 2012). "In addition, the study of SIRT1 knock-in mice indicated that SIRT1 functioned to maintain neovascularization capacity in response to DLL4 stimulation in the tumor vascular endothelium." (PMID 23028940, 2012). "SIRT1 also enhanced tumor neovascularization and tumor growth of LLC xenografts." (PMID 23028940, 2012). "SIRT1 has been reported to inhibit inflammation, transformation, tumor promotion, and progression." (PMID 23050959, 2012). "SIRT1, a nuclear enzyme and the most extensively studied family member, has been described as a guardian against cellular oxidative stress and DNA damage and, potentially, a tumor suppressor." (PMID 22860104, 2012). "SIRT1 has also been suggested to have a critical role in tumorigenesis, however it is controversial whether SIRT1 is a tumor-suppressor or a tumor-promoter and in fact it is likely to be tumor-type specific." (PMID 22479397, 2012). "All these drug resistant effects of SIRT1 could possibly be due to its anti-apoptotic effect and silencing of tumor suppressor genes." (PMID 22363646, 2012). "SIRT1 is supposed to be underexpressed in tumors if it is indeed a tumor suppressor." (PMID 23050959, 2012). "In hypoxic models in vitro and in in vivo models of systemic hypoxia and xenograft tumor growth, knockdown of SIRT1 protein with shRNA or inhibition of its activity with small molecule inhibitors impaired the accumulation of HIF-1α protein and the transcriptional increase of its target genes." (PMID 22479397, 2012). "In addition, SIRT1 inhibition resulted in growth inhibition in a mouse xenograft tumor model of HCC." (PMID 22479397, 2012). "Furthermore, in the SIRT1 transgenic mice, tumor growth was decreased when the deacetylase activity of SIRT1 was blocked with the administration of the class III HDAC inhibitor nicotinamide." (PMID 23028940, 2012). "SIRT1 may therefore play a critical role in tumor initiation and progression by blocking apoptosis and/or promoting cell growth." (PMID 21698133, 2011).
tumor (continued). "SirT1 is overexpressed in many tumor types including prostate, colon, leukemia, and lymphoma." (PMID 21307403, 2011). "In contrast to these observations, and as SirT1 is considered important in organism survival, a tumor suppressor function might be also anticipated." (PMID 21307403, 2011). "Significant debate currently exists regarding whether SIRT1 is a tumour-promoter or a tumour-suppressor, and whether SIRT1 can mediate lifespan extension via caloric restriction in higher organisms." (PMID 20975832, 2010). "Moreover, additional knockdown of SIRT1 in SENP7-overexpressing B cells suppressed tumour growth." (PMID 41362746, 2026). "Additionally, exosomal miR-4669 contributed to the polarization of M2 macrophages by increasing sirtuin 1, which led to acquired resistance to sorafenib, promoted tumor aggressiveness and immunosuppressive tumor microenvironment, thus influencing the recurrence of HCC." (PMID 40264760, 2025). "Additionally, in mouse models deficient in SETD2—a histone methyltransferase that catalyzes H3K36 trimethylation—tumorigenesis is promoted due to the inhibition of the SIRT1/FOXO signaling pathway, highlighting SIRT1’s role downstream of SETD2 in regulating tumor progression." (PMID 40567502, 2025). "SIRT1 may function in a context-dependent manner to exert tumor-promoting or suppressing qualities." (PMID 40507674, 2025). "Furthermore, by investigating the link between SIRT1 expression and immune cell infiltration in the tumor microenvironment, our study offers new insights into the immunological implications of SIRT1, an aspect that has not been fully explored in previous research." (PMID 41020376, 2025). "In addition, SIRT1 regulates autophagy to support tumor cell survival under metabolic stress." (PMID 41008982, 2025). "However, the increased SIRT1 expression observed in metastatic regions indicates its potential role as a tumor promoter and modulator of the tumor microenvironment, possibly through FoxO3a and miR-34a signaling, thereby enhancing cellular proliferation and invasion." (PMID 41816745, 2025). "Similarly, miRNA-29c acts as a tumor suppressor by inhibiting SIRT1 in HCC." (PMID 40149420, 2025). "Finally, tumor heterogeneity may lead to variable responses or resistance to SIRT1-targeted therapies." (PMID 41008982, 2025). "Interestingly, Sirt1 could have dual functions as a tumor promoter and a tumor suppressor at different stages of CRC, but Sirt1 inhibition has been reported to sensitize CRC cells to the apoptotic effect of chemotherapeutics." (PMID 39061884, 2024). "However, SIRT1 is a controversial protein with dual roles; it may enhance tumor growth or prevent tumorigenesis." (PMID 39195514, 2024).
tumor (continued). "Specifically, SIRT1, SIRT2, SIRT6, and SIRT7 are implicated in promoting PCa progression, while SIRT5 displays a paradoxical role, simultaneously aiding DNA repair and inhibiting apoptosis, yet fostering tumor growth through androgen receptor (AR) interactions." (PMID 39796040, 2024). "Importantly, SIRT1 is involved in tumor progression and the therapeutic response." (PMID 38443596, 2024). "Nude mice with HeLa xenografts overexpressing SIRT1 were described to develop bigger tumours 55 but this could be achieved independently of Wnt/β-catenin signalling given the pleiotropic effects of SIRT1 on global transcription, genome stability, and metabolism." (PMID 39494323, 2024). "Therefore, it is possible to speculate that cytoplasmic (aberrant) SIRT1 localization promotes tumor growth, while nuclear localization may act as a tumor suppressor, as suggested by our findings." (PMID 39766219, 2024). "However, the results of our pilot study are in support of SIRT1’s tumor suppressor role in canine mammary gland cancer, as we showed, for the first time, reduced immunoexpression and a shift from nuclear to cytoplasmic localization, which was linked to increasing grades of malignancy." (PMID 37627400, 2023). "However, some studies indicate that metformin can both stimulate and inhibit SIRT-1 expression in tumors, indicating that SIRT-1 may act as a tumor suppressor or oncogene depending on the type of tumor." (PMID 36678613, 2023). "Moreover, activation of SIRT1 delayed tumor growth and reduced tumor number in vitro." (PMID 38006398, 2023). "In addition, exosomal miR-9 transferred by MM tumor cells targets HDACs and Sirt1." (PMID 37048103, 2023). "Finally, we confirmed both in vitro and in vivo that CCL3 could activate VIRMA and its critical downstream target SIRT1, which fuels tumor metastasis in ICC." (PMID 36691046, 2023). "The discrepancy between the levels of SIRT1 protein expression and activity in tumor samples may solve the controversy previously reported regarding the use of SIRT1 as a tumor biomarker and poses the question of how 1,25(OH)2D3 specifically enhances SIRT1 deacetylase activity." (PMID 37530744, 2023). "SNHG10 via sponging miR-543 could upregulate tumor suppressive SIRT1 in NSCLC." (PMID 37441551, 2023). "Furthermore, SIRT1 can exhibit distinct expression patterns at various stages of tumor development." (PMID 38117829, 2023). "However, SIRT1 can act as either a tumor suppressor or a tumor promoter." (PMID 37338718, 2023). "However, some studies have found that SIRT1 acts as a tumor suppressor gene in cancer tissues." (PMID 38189049, 2023). "However, SIRT1 can act as a tumor suppressor by activating PTEN." (PMID 37175631, 2023). "In addition, it explores diverse upstream regulators and some natural/synthetic activators of SIRT1 as a possible treatment for inflammatory responses and tumor occurrence which may encourage the development of new anti-inflammatory drugs." (PMID 36081910, 2022). "Indeed, our finding is in accordance with a recent study showing that the overexpression of SIRT1 in liver tumoral cells contributes to the accumulation of p62 and activation of mTOR, thus inhibiting autophagy and contributing to tumor progression and poor prognosis in patients." (PMID 34952202, 2022). "Put together, all the evidence collected from the literature support our hypothesis that SIRT1 is a novel downstream transcriptional target of CD44/HA regulating pro-metastatic signalling pathways that are involved in tumour proliferation, migration, and invasion." (PMID 36505828, 2022). "However, SIRT1 functions as a tumor suppressor but is also involved in tumorigenesis." (PMID 35054489, 2022). "In addition, co-treatment with EX527 markedly reduced the proportion of cleaved caspase-3 positive cells and Bax expression, but enhanced Bcl2 levels in gAcrp-treated tumors, indicating that inhibition of SIRT-1 prevented tumor cells from apoptosis by adiponectin." (PMID 34986886, 2022).
tumor (continued). "Indeed, as reported by Suzuki and colleagues, SIRT1 activation might facilitate tumour cell migration across vascular endothelial cell layer, stimulating the increase in VEGF levels, thereby promoting metastasis through enhanced angiogenesis." (PMID 36235072, 2022). "This adds confidence that SIRT1 may be a promising vulnerability of tumor cells that are undergoing and/or have previously undergone oxidative damage to their DNA and/or have lowered ability to repair such damage (the current analysis does not distinguish between these scenarios)." (PMID 35614096, 2022). "Additionally, SIRT1 may be involved in the regulation of multiple aspects of tumor resistance by modulating the adaptive response of tumor cells." (PMID 34381712, 2021). "Therefore, the use of MSCs-Sirt1 is presented as a therapeutic option and opens the possibility of finding other regulatory proteins capable of reversing the immunomodulation exerted by MSCs in the tumor context." (PMID 34149687, 2021). "Furthermore, SIRT1, through MMP2 regulation, is implicated in tumor metastasis." (PMID 33917352, 2021). "Interestingly, low SIRT1 levels were detected in 70 cirrhotic HCC patients carrying the rs7895833 variant, and SIRT1 reduction was inversely correlated with high AFP, Child–Pugh score and tumor stage." (PMID 33920670, 2021). "In addition, the association between tumor response and SIRT1 expression was not statistically significant (p = 0.940)." (PMID 34638362, 2021). "However, such molecular mechanisms underlying the progress of tumor by SIRT1 have not been reported." (PMID 32398958, 2020). "Consequently, SIRT1 and SIRT3 are important regulators of tumour cell survival and cell function in the tumour microenvironment, with SIRT1 overexpression in mesenchymal stem cells (MSC) enhancing NK cell attraction, thereby shifting MSC effects from potentiating to supressing tumour progression." (PMID 33375613, 2020). "Therefore, understanding the roles of autophagy and SIRT1 in specific contexts, tumor microenvironments, and different stages is essential to apply autophagy- and SIRT1-driven strategies for the prevention of CRC development and reduction of CRC malignancy and progression." (PMID 31906264, 2020). "This may suggest that elevated expression of PD-1, TIM-3, CTLA-4, TIGIT, TOX, TOX2, and SIRT1 genes in the TME of CRC is induced by tumor-associated, factors, unlike VISTA, and LAG-3." (PMID 32393998, 2020). "Similarly, SIRT1 was also significantly overexpressed in ESCC comparatively to paired normal epithelium and associated with late tumour stage, TNM stage, positive lymph node status and worse overall and disease-free survival, constituting an independent prognostic factor for ESCC." (PMID 32429269, 2020). "However, either SIRT1 acts similarly as a tumor promoter or tumor silencer remains dubious." (PMID 32607257, 2020). "However, there are studies indicating the role of SIRT1 as a tumor suppressor." (PMID 32489467, 2020). "However, recent studies suggest that SIRT1 may act as a tumor suppressor or tumor promoter, depending on SIRT1 localization and cell type." (PMID 32485811, 2020). "Moreover, knockdown of Sirt1 by mRNA abrogated the anti-tumor effects of resveratrol against CRC colonosphere formation, invasion and increased the number of colonosphere formations and migrated cells in the 3D alginate-culture in TME similar to control multicellular-TME." (PMID 32962102, 2020). "Following activation, SIRT1 participates in a plethora of cellular processes such as cell senescence, apoptosis, DNA damage repair, cell cycle, oxidative stress response, energy metabolism regulation, tumor generation, and other physiological and pathological processes." (PMID 33292452, 2020).